GRIN2A (glutamate ionotropic receptor NMDA type subunit 2A)
Diseases named in the same sentence as GRIN2A in open-access papers (continued):
Sharing a sentence is not in itself a finding about the gene and the disease.
alcohol dependence (6 papers, 2013 to 2021). Physical and psychological dependence on alcohol. "GRIN2A has also recently been shown to be of the highest relevance in human alcohol dependence, among 10 glutamatergic neurosignaling genes, and in heroin addiction, among 6 glutamatergic neurosignaling genes." (PMID 23940648, 2013). "Especially, alcoholism (hsa05034) pathway exhibits the highest number of target connections (degree = 12), which includes consequential target genes such as MAOA, GRIN2A, GRIN2B, and CALM1." (PMID 32182911, 2020).
breast carcinoma (6 papers, 2016 to 2024). "For example, in CD4+ T-cells, BCL9 for B-cell acute lymphoblastic leukemia (B-ALL); GAS7 and PRDM16 for Acute myelogenous leukemia (AML); ESR1 for breast cancer; and GRIN2A for colorectal, lung, and gastric carcinoma were differentially methylated between PWH and PWoH." (PMID 38466776, 2024).
diabetes (6 papers, 2008 to 2024). "Here, we observed that, for example, GRIN2A was suggested to relate to the number of depressive episodes, the presence of alcohol abuse, and the polygenic contribution to chronotype, diabetes and hypertension in both major types of BP." (PMID 38865039, 2024). "All 7 confirmed neuronal function-related genes (DCAMKL1, GAT3, GRIN2A, KCNE2, PCGF1, PEPT2, ZNF219) revealed reproducible decreases at 3 months of STZ-induced diabetes." (PMID 18554398, 2008). "In contrast to these results, Pcgf1 and Grin2a showed significantly decreased expression with diabetes as compared to nondiabetic controls." (PMID 21633715, 2011).
Huntington disease (6 papers, 2011 to 2022). Huntington disease (HD) is a rare neurodegenerative disorder of the central nervous system characterized by unwanted choreatic movements, behavioral and psychiatric disturbances and dementia. "The aim of this study was to replicate association of variations in the N-methyl D-aspartate receptor subtype genes GRIN2A and GRIN2B in the “REGISTRY” cohort from the European Huntington Disease Network (EHDN)." (PMID 21989477, 2011).
developmental and epileptic encephalopathy (5 papers, 2019 to 2025). An epilepsy associated with developmental impairment that may be due to either the underlying etiology or the superimposed epileptic activity, or both.
colorectal cancer (4 papers, 2011 to 2023). A primary or metastatic malignant neoplasm that affects the colon or rectum. "Furthermore, GRIN2B and GRIN2A genes have been found to be highly methylated in various carcinomas: GRIN2B in esophageal, head, and neck squamous carcinomas, gastric cancer, and lung adenocarcinomas; and GRIN2A in colorectal cancer tissues." (PMID 36768862, 2023).
glaucoma (4 papers, 2017 to 2023). Increased pressure in the eyeball due to obstruction of the outflow of aqueous humor. "Only chr 4_ 44595667_44595116_-551 corresponded to the expression change of GRIN2A in the macaque glaucoma LGN samples." (PMID 35741665, 2022). "The results revealed that GRIN2A was more greatly decreased in the macaque glaucoma models than in the control samples." (PMID 35741665, 2022). "Results: circXPO5 significantly decreased in the glaucoma model and a ceRNA network analysis revealed that circXPO5 can bind to miR-330-5p, which also binds to GRIN2A (ionotropic receptor NMDA type subunit 2A)." (PMID 35741665, 2022). "After the GO pathway analysis, the “Ion channel activity” pathway would possibly be one of the most changed in macaque glaucoma models, which includes GRIN2A." (PMID 35741665, 2022).
lung adenocarcinoma (4 papers, 2016 to 2023). A carcinoma that arises from the lung and is characterized by the presence of malignant glandular epithelial cells. "In comparison, GRIN2A mutations have relatively higher prevalence in TCGA cohorts of lung adenocarcinoma, squamous cell carcinoma, or in cutaneous melanoma, and PIK3CA mutations, in lung adenocarcinoma and squamous cell carcinoma." (PMID 32014051, 2020). "The results showed that ACAN, CDKN3, GRIN2A, IL17A, KCNQ2, TIMP1, and UCHL1 were significantly up-regulated in lung adenocarcinoma cells." (PMID 36147496, 2022).
mental disorder (4 papers, 2017 to 2026). A disease that has its basis in the disruption of mental process. "Among the 25 individuals with mental disorders, the underlying pathogenic or likely pathogenic GRIN2A variants comprised 23 GRIN2Anull and two GRIN2Amissense." (PMID 41087560, 2026). "With the currently largest international cohort of individuals with disease-causing GRIN2A variants, we identify that GRIN2Anull variants significantly increase risk for a variety of mental disorders." (PMID 41087560, 2026). "To determine the prevalence of mental disorders among individuals with GRIN2A-related disorders, we enquired the presence of psychiatric symptoms in 235 individuals with pathogenic variants in GRIN2A who had previously enrolled in our global GRIN registry." (PMID 41087560, 2026). "We obtained data on the presence or absence of mental disorders for 121 individuals carrying pathogenic variants in GRIN2A, comprising 25 individuals with mental disorders and 96 without." (PMID 41087560, 2026).
glioma (3 papers, 2013 to 2023). A benign or malignant brain and spinal cord tumor that arises from glial cells (astrocytes, oligodendrocytes, ependymal cells). "The neurotransmitter glutamate, which mediates synaptic transmission through the N-methyl-D-aspartate glutamate receptors 2A and 2B (GRIN2A and GRIN2B) that appear in the PCST network, can promote glioma cell growth, and this pro-proliferative effect in U87MG cells is due to EGFR signaling." (PMID 23408876, 2013).
temporal lobe epilepsy (3 papers, 2019 to 2024). A localization-related (focal) form of epilepsy characterized by recurrent seizures that arise from foci within the temporal lobe, most commonly from its mesial aspect. "Limited to patients with temporal lobe epilepsy, we detected a significant correlation between the exponent and the cortical expression of GABRA1, GRIN2A, GABRD, GABRG2, KCNA2 and PDYN genes." (PMID 39056027, 2024).
brain trauma (2 papers, 2017 to 2021). "Despite several limitations of this study including uneven distribution of sex and race between groups, and the time of initial assessment, the results of this study suggest that genetic polymorphism in GRIN2A promoter could be a useful predictive marker of athlete susceptibility to concussion." (PMID 30202567, 2017). "Genetic polymorphisms in the genes contributing to plasticity and repair (APOE), synaptic connectivity (GRIN2A), calcium influx (CACNA1E), uptake and deposit of glutamate (SLC17A7) are potential biomarkers of concussion incidence and recovery rate." (PMID 30202567, 2017).
colon adenocarcinoma (2 papers, 2016 to 2018). "Recently, GRIN2A have been identified as a novel hub driver gene for the stage-II progression of colon adenocarcinoma." (PMID 29871594, 2018). "We have identified DYNC1H1,GRIN2A, and GRM1 as novel hub driver genes for the stage-II progression of colon adenocarcinoma." (PMID 27243824, 2016).
eating disorder (2 papers, 2020). A broad group of psychological disorders with abnormal eating behaviors leading to physiological effects from overeating or insufficient food intake. "Grin2A encodes the NR2a subunit of NMDARs, which are associated with hyperactivity disorders and eating disorders, including AN." (PMID 32499508, 2020).
heroin addiction (2 papers, 2011 to 2013). "Genotype and allele frequencies of the GRIN2A gene SNPs in cases and controls and the results of their associations with risk of heroin addiction." (PMID 23940648, 2013). "In this study, we investigated forty loci in a Chinese population from Shaanxi province to verify the putative association between GRIN2A polymorphisms and heroin addiction." (PMID 23940648, 2013). "An association of GRIN2A single-nucleotide polymorphisms (SNPs) with heroin addiction was found earlier in African Americans." (PMID 23940648, 2013). "To identify markers that contribute to the genetic susceptibility to heroin addiction, we examined the potential association between heroin addiction and forty polymorphisms of the GRIN2A gene using the MassARRAY system and GeneScan in this study." (PMID 23940648, 2013). "Our results provide direct evidence that a genetic change in GRIN2A is linked to heroin addiction in humans, and extends the list of variants that may affect the development of heroin addiction." (PMID 23940648, 2013). "GRIN2A haplotype frequencies and the results of their associations with risk of heroin addiction." (PMID 23940648, 2013). "Recent studies suggested that polymorphisms in the N-methyl D-aspartate 2A (GRIN2A) gene may be associated with drug addiction, including alcohol and heroin addiction." (PMID 23940648, 2013). "We hypothesized that common variants in the GRIN2A might contribute significantly to the predisposition to develop heroin addiction." (PMID 23940648, 2013). "Genetic polymorphisms in GRIN2A have a plausible role in modulating the risk of heroin addiction." (PMID 23940648, 2013). "In this study, we evaluated the association between thirty-nine SNPs that efficiently tag the common variation in the GRIN2A gene and heroin addiction." (PMID 23940648, 2013). "The statistics of the GRIN2A (GT)n repeat in heroin addiction and controls." (PMID 23940648, 2013).
acute myocardial infarction (1 paper, 2025). Necrosis of the myocardium, as a result of interruption of the blood supply to the area. "GRIN2A was considered a candidate biomarker of acute myocardial infarction, which is closely related to PAH." (PMID 40357364, 2025).
AIDS (1 paper, 2024). A syndrome resulting from the acquired deficiency of cellular immunity caused by the human immunodeficiency virus (HIV). "One observational clinical study suggests that overall NMDAR expression is reduced in the frontal cortex of individuals with AIDS and HAD, whereas we observe increased Grin1 and Grin2a transcript expression specifically in rat mPFC." (PMID 38514527, 2024).
atrioventricular septal defect (1 paper, 2014). "For example, the de novo missense mutation c.4354C>T (p.1452R>C) in GRIN2A (MIM 138253, ENST00000461292) was found in F2, a female with atrioventricular septal defect (AVSD), hepatic dysfunction, polydactyly, panhypopituitarism and brain injury." (PMID 24476948, 2014).
bladder cancer (1 paper, 2025). "Additionally, structural changes involving the GRIN2A gene, such as amplifications and translocations, have been previously documented in bladder cancer." (PMID 40893790, 2025).
childhood-onset schizophrenia (1 paper, 2023). "GRIN2A variants have been associated with a range of neuropsychiatric disorders including adult-onset psychotic spectrum disorder and childhood-onset schizophrenia." (PMID 37107537, 2023). "In addition to the SCHEMA study, rare de novo GRIN2A mutations are believed to contribute to sporadic cases of adult-onset schizophrenia, and common variation in GRIN2A (polymorphisms rs7206256 and rs11644461) appears to influence the risk of childhood-onset schizophrenia." (PMID 37107537, 2023).
Dystonia (1 paper, 2022). An abnormally increased muscular tone that causes fixed abnormal postures. "Similarly, GRIN2A and CACNA1B mutations have been found in dystonia and other movement disorders." (PMID 35773312, 2022).
emotional dysregulation (1 paper, 2023). "We identified several molecular markers, including Dgkh, Arfgef3, Kcnh7, Grin2a, Tenm1 and Epha6, implicated in neurodevelopmental deficits and psychiatric conditions featuring impaired cognition and emotional dysregulation." (PMID 37542675, 2023).
gastric adenocarcinoma (1 paper, 2024). "Three of those, HENMT1, GRIN2A, and STC2, seem to relate to processes such as hypoxia response and hormone-metabolism regulation, thereby contributing to the development and progression of several carcinomas, including gastric adenocarcinomas." (PMID 38542354, 2024).
Generalized Epilepsies (1 paper, 2021). "Significance: This study revealed GRIN2A gene was potentially a candidate pathogenic gene of idiopathic generalized epilepsies." (PMID 34720871, 2021).
gliosarcoma (1 paper, 2020). A rare histological variant of glioblastoma (WHO grade IV) characterized by a biphasic tissue pattern with alternating areas displaying glial and mesenchymal differentiation (WHO). "Based on the trace VAF of GRIN2A mutation in the initial gliosarcoma and on the absence of ATM mutation in the frontal recurrence, the initial tumor most likely contained few genetically distinct subpopulations that gave rise to the various subsequent tumors." (PMID 32014051, 2020).
metastatic melanoma (1 paper, 2014). A melanoma that has spread from its primary site to another anatomic site. "In conclusion, our study suggests that non-synonymous mutations in GRIN2A are present in approximately 20% of patients with metastatic melanoma and associate with faster disease progression and shorter overall survival." (PMID 24455489, 2014).
metastatic tumors (1 paper, 2024). "In addition to these molecular alterations, amplification of MYC, HSP90AB1, and VEGF-A and mutation of GRIN2A were present in the metastatic tumors." (PMID 38837109, 2024). "While MYC amplification was an acquired molecular event (included in the NGS panel used for the initial and metastatic tumor), it is not clear whether HSP90AB1, VEGFA, or GRIN2A were present at the time of initial diagnosis." (PMID 38837109, 2024).
mucinous adenocarcinoma (1 paper, 2025). An invasive adenocarcinoma composed of malignant glandular cells which contain intracytoplasmic mucin. "We detected both previously reported (HNF1, SUFU) and unreported (BRCA2, GRIN2A) alterations associated with mucinous adenocarcinoma." (PMID 40302146, 2025).
myocardial infarction (1 paper, 2025). Gross necrosis of the myocardium, as a result of interruption of the blood supply to the area, as in coronary thrombosis. "GRIN2A is related to myocardial infarction, yet no direct research on its connection with PAH has been reported." (PMID 40357364, 2025).
Myoclonus-Dystonia (1 paper, 2022). "Remarkably, SGCE, CACNA1B, and GRIN2A are well-known for causing Myoclonus-Dystonia (M-D), a hyperkinetic movement disorder that resembles tics, which is found in a subgroup of PANS." (PMID 35773312, 2022).
nematode infection (1 paper, 2019). "In response to maternal nematode infection, expression of both NR2A and NR2B (also known as Grin2A and Grin2B) genes was higher in the P7 brain." (PMID 30862816, 2019). "Two sub-units of NMDARS, NR2A and NR2B (also known as Grin2A and Grin2B) as well as several AMPARs including the metabotropic glutamate receptors 1 and 2 (mGlu-R1 and mGlu-R2), Gria3, Grm2, Grm4, Grik3 and Grik5 were up-regulated in the pup brain on P7 in response to maternal nematode infection." (PMID 30862816, 2019).
polycystic ovary syndrome (1 paper, 2022). A disorder that manifests as multiple cysts on the ovaries. "Two genes (GRIN2A and ITGAX) located on BTA25 were associated with CTFS in Iranian Holstein cattle and with altered expression in polycystic ovary syndrome in women, respectively." (PMID 35484513, 2022).
prion disease (1 paper, 2021). A transmissible disease that is caused by a protein that is able to induce abnormal folding of normal cellular proteins, leading to characteristic spongiform brain changes, which are associated with neuronal loss without an inflammatory response. "We further show that systemic bacterial infection results in a significant reduction of Grin2a expression, especially at the early stage of ME7 prion disease." (PMID 35058740, 2021). "Analysis of activity-related neuronal receptors which are involved in development of LTP and LTD, such as Grm1 and Grin2a, showed a decrease in response to ME7 prion disease and were significantly lower following systemic exposure to S. typhimurium." (PMID 35058740, 2021).
sarcopenia (1 paper, 2024). Progressive decline in muscle mass due to aging which results in decreased functional capacity of muscles. "However, there’s limited research on the role of GRIN2A in frailty and sarcopenia; our study suggests it might regulate sarcopenia through its interaction with glycine, though further experimental validation is needed." (PMID 38415056, 2024).
vaginal infection (1 paper, 2022). "In this study, during the acute infection phase of the HSV-2 mouse model of vaginal infection, the quantitative analysis of LFQ protein showed that the expression of GluN2A encoded by Grin2a increased in the mouse brain tissue, but no significant changes in the expression of Aβ were detected." (PMID 36061859, 2022).
neurodevelopmental disorder (28 papers, 2014 to 2026). A behavioral and cognitive disorder with onset during the developmental period that involves impaired or aberrant development of intellectual, motor, or social functions. "Pathogenic germline variants in GRIN2A are associated with neurodevelopmental disorders and developmental and epileptic encephalopathy." (PMID 40565021, 2025). "It has been shown that mutations in grin2A induced a decrease in GluN2A expression and led to complex neurodevelopmental disorders that include the occurrence of seizures." (PMID 33897358, 2021). "They showed that GRIN2A variants are commonly associated with an epileptic phenotype but that GRIN2B variants are commonly found in patients with neurodevelopmental disorders." (PMID 34685369, 2021). "For example, it has been suggested that GRIN2A mutations predominantly lead to an epileptic phenotype while GRIN2B variants are more likely to lead to neurodevelopmental disorders." (PMID 34776984, 2021). "Human NMDAR genes are highly intolerant to variations, and mutations in Grin2a and Grin2b, the genes encoding the GluN2A and GluN2B subunits, respectively, are a major cause of neurodevelopmental disorders associated with childhood epilepsy and cognitive impairments." (PMID 34354080, 2021). "This partially encompasses the GRIN2A and USP7 genes associated with neurodevelopmental disorders, including autistic features." (PMID 38539661, 2024). "Such variants were identified in GRIN2A and GRIN2B genes in individuals diagnosed with neurodevelopmental disorders." (PMID 38214768, 2024). "We identified 48 variants in the M3 transmembrane helix across GRIN1, GRIN2A, and GRIN2B in 56 patients with neurological and/or neurodevelopmental disorders." (PMID 38538865, 2024). "Mutations in GRIN2A and GRIN2B encoding the alpha and beta-2subunits (NR2A and NR2B) of the glutamate-activated N-methyl-D-aspartate (NMDA) receptor areassociated with several neurodevelopmental disorders." (PMID 24272827, 2014). "Additionally, variation in GRIN2A (the gene for the NR2A subunit) is commonly associated with an epileptic phenotype, while that in GRIN2B (the gene for the NR2B subunit) is commonly found in patients with neurodevelopmental disorders." (PMID 32093213, 2020).